IGF1 (insulin like growth factor 1)
Diseases named in the same sentence as IGF1 in open-access papers (continued):
Sharing a sentence is not in itself a finding about the gene and the disease.
lymphoma (18 papers, 2006 to 2023). A malignant (clonal) proliferation of B- lymphocytes or T- lymphocytes which involves the lymph nodes, bone marrow and/or extranodal sites. "It is possible the effect of fasting on AE associated with vincristine, and glucose, insulin and IGF‐1 concentrations vary with patient stage and immunophenotype of lymphoma." (PMID 33448618, 2021). "AOiGHD females showed lymphomas in multiple tissues and developed severe OA, despite reductions in GH/IGF‐1 levels." (PMID 34240807, 2021). "Recently, EBERs were found to increase transcription or mRNA stability of IL-10, IL-9, or IGF1 in lymphoma or carcinoma cell lines." (PMID 20144199, 2010). "Low IGF-1 concentrations might also occur in cats newly diagnosed with DM as well as in cats with lymphoma and, depending on the assay, also in aging animals." (PMID 37756097, 2023). "Strikingly, strong expression of genes encoding growth factors IGF-1 and PDGF-CC, which have been shown potently to protect cells from apoptosis, firmly indicates that SS-TAMs provide trophic cues in the lymphoma microenvironment with the potential to promote net population growth." (PMID 25702581, 2015). "The 4‐circulating miRNA signature correlated with aberrant Ras protein signal transduction via IGF1 and JUN expression, and MDSC‐ and Th17 cell‐dependent lymphoma progression." (PMID 33107145, 2021). "Next, to validate downregulation of the PI3K/AKT/mTOR pathway in Eμ-Myc lymphomas upon PRDM15 depletion, we starved WT and KO cells overnight and subsequently stimulated them with insulin and IGF1." (PMID 32665551, 2020). "IGF1 and JUN were two key regulators of Ras cascade, and enhanced lymphoma development." (PMID 33107145, 2021). "We further explored DLCBL proliferation by treatment with DCZ3301 in the presence or absence of interleukin-6 (IL-6) and insulin-like growth factor-1 (IGF-1), given that cytokines have an important role in lymphoma growth and survival." (PMID 29022919, 2017).
meningioma (18 papers, 2010 to 2024). A generally slow growing tumor attached to the dura mater. "There was a weak positive correlation between IGF-1 level and GH basal level and meningioma size, but the sample size was relatively small even with integration of NYU patient data." (PMID 38919490, 2024). "In that study, meningioma cells were treated with IGF-1 alone, fenretinide alone, or a combination of both agents." (PMID 38919490, 2024). "IGFs, particularly IGF-1, bind to their receptors on meningioma cells, activating intracellular signaling cascades such as the PI3K/Akt and Ras/Raf/MEK/ERK pathways, which promote cellular proliferation and survival." (PMID 39188673, 2024). "Meningiomas express GH receptors, and in vitro activation of the GH/IGF-1 axis increases the growth rate of meningiomas." (PMID 30137467, 2019). "Despite the limitations of the small sample size of the study there could be a positive correlation between GH and IGF-1 levels and meningiomas in patients with coexisting tumors." (PMID 38919490, 2024). "In an in vivo model, downregulation of the GH/IGF-1 axis reduced meningioma growth." (PMID 30137467, 2019). "A recent study reported that meningioma of PAM may be associated with GH and IGF-1 levels and radiology." (PMID 31665029, 2019). "Meningiomas are closely associated with ossification and calcification, and the involvement of bone morphogenetic protein (BMP), insulin-like growth factor-1, endothelin-1, and osteoprotegerin has been investigated, but any function in meningioma cells is still unknown." (PMID 38446374, 2024). "Thus, it is feasible that the correlation between IGF-1 level and meningioma size – a relationship well-established in prior literature – is dampened in our review by the effect of agents like retinoids and other undisclosed chemicals in our pooled patient population." (PMID 38919490, 2024). "In fact, more than half of meningiomas overexpress IGF-1 receptors, and IGF-1 can promote the growth of meningioma cells in vitro." (PMID 34970226, 2021). "We found that several growth factors including EGFL6, IGF1, FGF2, FGF7, FGF9, and FGF11 were overexpressed in fibroblastic meningioma, especially EGFL6 gene with extremely high expression in benign meningioma tissues." (PMID 23285163, 2012). "Analysis of data from literature review showed that GH and IGF-1 levels did not have strong correlations with meningioma size." (PMID 38919490, 2024). "Due to the scarcity of data, not many conclusions can be drawn regarding IGF-1 and GH levels and meningioma size." (PMID 38919490, 2024). "Finally, laboratory studies have confirmed that IGF1, IGF2, and IGF1R genes are overexpressed in meningioma." (PMID 24587258, 2014). "While no clear correlation between GH or IGF-1 level and meningioma size was identified in our review, previous studies have suggested that these hormones play a dominant role in the pathogenesis of meningiomas." (PMID 38919490, 2024). "We were not able to collect IGF-1 data for the cohort, but future research would be improved by investigating, if practical, whether IGF-1 levels during GH treatment relate to subsequent meningioma risk." (PMID 30137467, 2019).
psoriasis (18 papers, 2012 to 2026). An autoimmune condition characterized by red, well-delineated plaques with silvery scales that are usually on the extensor surfaces and scalp. "Moreover, IGF-1 factor was found to be associated with skin abnormalities, cause localized or diffuse hyperkeratotic plaques with or without hyperpigmentation, and increase the prevalence of VV and psoriasis, which is consistent with our study." (PMID 36506327, 2022). "The levels of fasting glucose, insulin, IGFBP3, and IGFBP6 were higher in patients with psoriasis, while the levels of IGF-1, IGF-1R, and IGBP4 were higher in controls." (PMID 41635444, 2026). "The novelty of our study is in its comprehensive assessment of the involvement of the IGF-1 signaling pathway in the pathogenesis of psoriasis and advances the understanding of the pathogenesis of psoriasis and its comorbidities." (PMID 41635444, 2026). "The IGF-1/IGF1R pathway is associated with numerous hyperplastic epidermal disorders, such as psoriasis." (PMID 35216228, 2022). "There are studies that have proposed that the extent and severity of psoriasis correlate with growth hormone (GH) levels, although psoriatic patients, in general, have normal GH and insulin-like growth factor (IGF-1) levels." (PMID 24707406, 2014). "Collectively, miR-625-3p may contribute to the pathogenesis of psoriasis through interference with IGF-1 signalling." (PMID 38433211, 2024). "This suggests that both treatments may be effective in reducing psoriasis severity and IGF-1 levels." (PMID 38202116, 2023). "The pathogenesis of psoriasis is due to the activation of immune cells and their secretion of cytokines, chemokines, growth factors, and IGF-1, which may lead to psoriatic epidermal hyperplasia and therefore it is considered one of the causes of psoriasis." (PMID 37373186, 2023). "IGF-1 appears to contribute to the epidermal hyperproliferation that characterises psoriasis." (PMID 31416218, 2019). "Similarly, miR-99a is down-regulated in psoriatic KC despite the high output of the IGF1 signaling pathway in psoriasis." (PMID 25208211, 2014). "At each step of the psoriasis molecular pathway, different inflammatory cytokines such as IL-6, IL-17, IL-22, and IL-23 are triggered, on the other side, growth factors such as EGF, VEGF, KGF, and IGF-1, which underscores the central role which predominantly drives epidermal hyperplasia." (PMID 33849555, 2021).
sleep disorder (18 papers, 2012 to 2025). A change from the patient's baseline sleeping pattern, in the hours slept and/or an alteration/dysfunction in the stages of sleep. "This patient's sleep disorder may contribute to the disruption of the cardiomyocyte circadian clock, which could activate GH/IGF-1 signaling and may be linked to hypertrophic cardiomyopathy." (PMID 40697972, 2025). "The positive effect of smoking on PSQI scores and sleep disturbances were negatively moderated by the levels of IGF1 in cerebrospinal fluid in Chinese adult males." (PMID 38800060, 2024). "Existing studies have found that serum IGF‐1 levels are significantly lower in patients with sleep disorders, and IGF‐1 concentration is negatively correlated with apnoea‐hypopnoea index and oxygen saturation index scores and positively correlated with minimum oxygen saturation." (PMID 40713933, 2025). "Furthermore, the reduction in both sleep duration and quality, alterations in circadian rhythm, and increased frequency of sleep disorders can lead to decreased secretion of growth hormone (GH), insulin-like growth factor-1 (IGF-1), and testosterone." (PMID 40359225, 2025). "Our study revealed that IGF1 played a moderating role in the process of smoking-induced sleep disorders, which, to some extent, could provide new insights into the association between cigarette smoking and sleep disorders." (PMID 38800060, 2024). "Sleep disorders might lead to frailty through dysregulation of various hormones (e.g., insulin-like growth factor-1 and testosterone), chronic inflammation, and other factors." (PMID 34744691, 2021). "The Growth Hormone/Insulin like growth factor-1 axis could play a role in the development of IR during sleep disorders." (PMID 28384333, 2017). "In addition, we checked the safety and tolerability of IGF1 treatment on other parameters: blood parameters, cardiorespiratory activity, bone density, brain activity, motor abilities, and eating and sleep disorders." (PMID 22934177, 2012). "Similarly, animal experiments and epidemiological studies have revealed that sleep disorders might inhibit the IGF1 axis, with circulating IGF1 levels significantly declining after sustained sleep deprivation." (PMID 38800060, 2024). "All studies involving men measured T or TT levels in relation to age, whereas some also analyzed DHEAS, IGF-1, BMI, type of work, andropause symptoms (with the AMS scale), job content (with the JCQ questionnaire), lifetime SEP, and sleep disorders." (PMID 34639376, 2021). "Sleep disorders and obstructive sleep apnea (OSA) may affect the growth hormone/insulin-like growth factor 1 (GH/IGF-1) axis with an inverse relationship between IGF-1 plasma concentration and the severity of OSA." (PMID 30294204, 2018). "Sleep disorders and OSA may affect the Growth Hormone/Insulin like growth factor 1 (GH/IGF-1) axis with an inverse relationship between IGF-1 plasma concentration and the severity of OSA, which could be the mechanism involved in the association between OSA and IR." (PMID 28384333, 2017).
viral infection (18 papers, 2011 to 2024). "Circulating IGF-1 levels have been correlated with viral infection and associated with HCC progression." (PMID 34452353, 2021). "It remains to be shown if any IGF-1 mediated delay in IFN-γ or other Th1 related responses, predisposes preterm neonates to a higher risk of intracellular bacterial and viral infections." (PMID 37648745, 2024). "To further link metabolic responses and inflammation, we assessed insulin signaling related genes, observing that viral infection significantly decreased transcriptional levels of igf1 and its receptor igf1r in the liver of IPNv challenged fish." (PMID 34768822, 2021). "The aim of this review is to summarize the current data obtained from virological studies and to increase our understanding of the complex role of the IGF-1 signaling axis in animal virus infections." (PMID 34452353, 2021). "In adult muscles, localized infusion of IGF-1 protein increased muscle mass, and muscle transfected with expression vectors for IGF-1 by electroporation or viral infection displays hypertrophy." (PMID 21040371, 2011). "Ongoing larger-scale studies in preterm infants, having lung development and BPD as main outcomes (ClinTrials registration NCT03253263) will help to clarify how IGF-1 supplementation may increase or decrease sensitivity to bacterial and viral infections." (PMID 37648745, 2024). "Viral infection can induce specific miRNAs, as revealed in studies of IGF-1 expression." (PMID 34452353, 2021). "The IGF-1 signaling pathway is required for certain viral effects in oncogenic progression and may be induced as an effect of viral infection." (PMID 34452353, 2021). "Additionally, circulating IGF-1 level was correlated with virus infection, Child–Pugh class, and BCLC stage of HCC patients." (PMID 29113370, 2017). "Twenty-four hours after virus infection, the cells were further stimulated by IGF1 for 30 min." (PMID 25826393, 2015). "The increased IGF-1 might come from both viral infection and cell secretion." (PMID 31338023, 2019).
Anorexia (17 papers, 2012 to 2025). Lack of desire to eat (loss of appetite). "Taking into account that the acute phase of inflammation is associated with anorexia, an inflammation-induced decrease in circulating IGF-1 could be secondary to the decrease in food intake." (PMID 34502376, 2021). "This again indicated that the suppressed GP Igf1 expression in CKD is in part secondary to anorexia and reduced nutrient intake." (PMID 32630463, 2020). "Chemotherapy-induced gastrointestinal disorders and anorexia could lead to starvation or low glucose levels, leading to decreased levels of insulin/IGF-1." (PMID 32709007, 2020). "Taken together, these results demonstrated that the AC extract has a protective effect against chemotherapy-induced muscle atrophy mainly by attenuating muscle proteolysis, pro-inflammatory cytokine production, and anorexia, and activating IGF-1-dependent protein synthesis." (PMID 29731967, 2018). "Not only does inflammation induce anorexia and decrease in food intake, it has also been recently reported that arginine administration to fasted mice is able to prevent GH resistance and to increase IGF-1 and body weight by decreasing the Toll-like receptor 4-mediated inflammatory pathway." (PMID 34502376, 2021). "Taken together, the KDE was well tolerated, attenuated anorexia, altered systemic metabolism, attenuated indices of tumor burden, and reduced skeletal muscle atrophy without changing circulating IGF‐1 and insulin levels, illustrating a unique and multifaceted anti‐CACS therapy." (PMID 32239651, 2020).
Atrophy (17 papers, 2005 to 2025). Any weakening or degeneration, especially through lack of use. "Muscle atrophy was caused not only by the disruption of the IGF1/PI3K/Akt/mTOR pathway signaling but also by the observed decrease in myogenin expression in aged fish, which also contributes to muscle degeneration." (PMID 38892357, 2024). "LIN can down-regulate the expression of Atrogin1 and MuRF1 through the IGF-1/Akt/FoxO pathway to alleviate DDP-induced muscle atrophy." (PMID 33390985, 2020). "Overproduction of myostatin and activins, inflammatory responses, and impaired insulin-like growth factor 1 (IGF-1)-dependent protein synthesis are known to be closely related to the pathogenesis of muscle atrophy." (PMID 32244785, 2020). "Additional pathways have been suggested to mediate DOX-induced cardiac atrophy including impaired insulin-like growth factor 1 (IGF-1) signaling, reactive oxygen species (ROS)-dependent upregulation of NADPH oxidase 2 (Nox2), altered PI3K-AKT pathway, and activated p38 MAPK." (PMID 36986490, 2023). "Taken together, magnolol may be a promising chemoprotective agent for the prevention of muscle atrophy through the upregulating M2c macrophages, which are a major source of IGF-1." (PMID 32117241, 2020). "Consistent with the results above, IGF-1, PI3K(p85α) and the downstream effectors (from IGF-1) were also decreased in the gastrocnemius muscles from Den-, Dex- and fasting-induced atrophy models." (PMID 28541289, 2017). "Of note, IGF-1 was earlier reported to stimulate collagen synthesis and fibroblast growth, and—if IGF-1 is suppressed by -induced oxidative stress—results in skin ageing and atrophy." (PMID 25520316, 2015). "In particular, the determination of protein level of the two IGF-1 sensitive genes MuRF1 and HDAC5 would deserve a focused investigation, also if it has been found that the MuRF1 mRNA modification during atrophy is often accompanied by corresponding changes in protein levels." (PMID 23755187, 2014).
hyperlipidemia (17 papers, 2009 to 2025). "A dominant hypothesis is that the hyperlipidemia associated with overnutrition results in increased pancreatic insulin release and/or increased production of insulin-like growth factor 1 (IGF-1) in the liver." (PMID 34429409, 2021). "Pituitary removal combined with HFD induced hyperlipidemia, characterized by elevated serum total TC, TG, and LDL‐C levels, and reduced serum HDL‐C and IGF‐1 levels in ApoE−/−‐Hx mice." (PMID 41089172, 2025). "Pituitary removal combined with HFD induced significant hyperlipidemia, characterized by elevated serum TC, TG, and LDL‐C, as well as reduced serum HDL‐C and IGF‐1 in C57‐Hx mice." (PMID 41089172, 2025).